FBN3 (fibrillin 3)
Description:
[Fibrillin-3]: Fibrillins are structural components of 10-12 nm extracellular calcium-binding microfibrils, which occur either in association with elastin or in elastin-free bundles. Fibrillin-containing microfibrils provide long-term force bearing structural support.
Synonyms: KIAA1776
Tractability: Antibody: UniProt places it where antibodies can reach, with high confidence; UniProt predicts a signal peptide or a membrane-spanning region; its Gene Ontology location is reachable by antibodies, with medium confidence.
Gene: Protein-coding gene on chromosome 19 (8,065,402 to 8,149,693, reverse strand). Ensembl gene ENSG00000142449.
Subcellular location: Secreted, extracellular space, extracellular matrix
Pathways (Reactome):
Extracellular matrix organization: Degradation of the extracellular matrix; Elastic fibre formation; Molecules associated with elastic fibres
Gene Ontology:
Molecular function: extracellular matrix structural constituent; hormone activity; calcium ion binding; extracellular matrix constituent conferring elasticity
Biological process: glucose homeostasis; glucose metabolic process; camera-type eye development; embryonic eye morphogenesis; signal transduction
Cellular component: extracellular matrix; extracellular region; non-collagenous component of interstitial matrix; microfibril
Genetic constraint (gnomAD): Loss-of-function variants: 229 observed, 302.63 expected, observed/expected ratio (o/e) 0.76, 90% interval 0.68 to 0.84. The upper end of that interval is the gene's LOEUF score, 0.84, which puts it in group 3 of 6, group 1 being the genes least tolerant of losing a copy. Missense variants: 3,574 observed, 3,802.2 expected, observed/expected ratio (o/e) 0.94, 90% interval 0.91 to 0.97. Synonymous variants: 1,450 observed, 1,482.1 expected, observed/expected ratio (o/e) 0.98, 90% interval 0.94 to 1.02.
Homologues: Orthologues: chimpanzee FBN3 (98% identical), macaque FBN3 (92% identical), pig FBN3 (86% identical), dog FBN3 (86% identical), rabbit FBN3 (72% identical), tropical clawed frog fbn3 (72% identical), zebrafish fbn2b (69% identical). Paralogues in human: FBN2 (68% identical), FBN1 (61% identical).
Diseases named in the same sentence as FBN3 in open-access papers:
FBN3 is named in the same sentence as 30 diseases in open-access papers, as found by Europe PMC text mining. Sharing a sentence is not in itself a finding about the gene and the disease. The quoted sentences say what the papers report.
Bardet-Biedl syndrome (3 papers, 2017 to 2025). A ciliopathy with multisystem involvement. "Recently, mutations of the less characterized fibrillin family member, FBN3, have been associated in a single family with Bardet–Biedl syndrome (BBS)." (PMID 35910214, 2022). "Mutations in FBN3 as well as in two other family members of the fibrillin-family FBN1 and FBN2 have been identified in several disorders, including Bardet–Biedl syndrome and Marfan syndrome." (PMID 41440000, 2025).
Obesity (3 papers, 2009 to 2022). Accumulation of substantial excess body fat. "All these data support the hypothesis that obesity, recorded in all the patients herein described, is caused by an increased TGF-β signaling determined by damaging FBN3 variants alternating an EGF-like domain." (PMID 35910214, 2022). "This study further supports that FBN3 is a candidate gene for a BBS-like syndrome characterized by developmental delay, cognitive impairment, obesity, dental, genital, and skeletal anomalies." (PMID 35910214, 2022).
polycystic ovary syndrome (3 papers, 2009 to 2022). A disorder that manifests as multiple cysts on the ovaries. "In fact, FBN3 deficiency is related to secondary amenorrhea because of its role in the pathogenesis of polycystic ovary syndrome." (PMID 29156830, 2017). "FBN3 seems to play a role in the pathogenesis of polycystic ovary syndrome 1 (PCOS1; MIM % 184700)." (PMID 35910214, 2022).
Marfan syndrome (2 papers, 2023 to 2025). A disorder of the connective tissue. "FBN3 encodes a member of the fibrillin protein family, mainly localized to extracellular microfibrils of developing skeletal elements, and responsible to Weill–Marchesani Syndrome and Marfan syndrome." (PMID 37658396, 2023).
Autoimmunity (1 paper, 2019). The occurrence of an immune reaction against the organism's own cells or tissues. "Variant FBN3 →TGFβ and Treg ↓ → development of autoimmunity;anovulation → E/P → autoantibodies ↑; SHBG↓ →free sex hormones↑." (PMID 30705778, 2019).
hyperlipidemia (1 paper, 2017). "FBN3 deficiency is also related to the congenital cardiovascular abnormalities in patient III1and hyperlipidemia and insulin resistant diabetes mellitus in patient III2 respectively." (PMID 29156830, 2017).
Insulin resistance (1 paper, 2023). Increased resistance towards insulin, that is, diminished effectiveness of insulin in reducing blood glucose levels. "Women with PCOS carrying allele 8 of D19S884 in the FBN3 gene had significantly lower levels of TGF-β1, higher inhibin β levels, and higher Homeostatic Model Assessment of Insulin Resistance levels than women with PCOS without the same allele." (PMID 37635968, 2023).
leukemia (1 paper, 2025). A malignant (clonal) hematologic disorder, involving hematopoietic stem cells and characterized by the presence of primitive or atypical myeloid or lymphoid cells in the bone marrow and the blood. "Besides lymphoma- and/or leukemia-related genes, the most frequently mutated tumor suppressor genes included AFAP1L1, FBN3, MTSS2, and TTLL5, with each being mutated in at least 10% of cHL cases." (PMID 41296384, 2025).
malocclusion (1 paper, 2024). "Materials and Methods: in this study, we investigated the correlation between the rs7351083 SNP of the FBN3 gene that encodes a member of the fibrillin protein family and malocclusion risk in a group of 57 patients from Romania." (PMID 39064490, 2024).
plasma cell tumor (1 paper, 2022). "In FBN3, Cys1406Ser occurs in the same cysteine where Cys1406Phe was found in plasma cell tumors." (PMID 36214621, 2022).
vitamin D deficiency (1 paper, 2020). A nutritional condition produced by a deficiency of VITAMIN D in the diet, insufficient production of vitamin D in the skin, inadequate absorption of vitamin D from the diet, or abnormal conversion of vitamin D to its bioactive metabolites. "While levels of TGF-β1 were confirmed to be found lower in HT as well as in PCOS women carrying allele 8 of D19S884 in the FBN3 gene, vitamin D deficiency was also seen to be decreased along with decreased Tregs." (PMID 33391917, 2020).
tumor (3 papers, 2013 to 2020). "Gene alterations associated with tumor grade progression in initial low grade tumors include FBN3, CIT and HECTD4." (PMID 29507699, 2018). "The function of FBN3, PCNXL3, SFXN3, SRGAP1, VN1R5 and WDR70 have been only marginally evaluated, and their role in the molecular signaling of tumor cells remains largely understudied." (PMID 23577124, 2013). "Compared with patients with tumor size no more than 5 cm, the mutation percentages of ALB, FBN3, HSPG2, and FLG2 were increased in patients with tumor size more than 5 cm." (PMID 32017470, 2020).
connective tissue disorder (1 paper, 2022). A disease involving the connective tissue. "FBN1, FBN2, and FBN3 encode the human fibrillins and mutations in FBN1 and FBN2 cause connective tissue disorders called fibrillinopathies, affecting cardiovascular, dermal, skeletal, and ocular tissues." (PMID 35910214, 2022).
mitochondrial disease (1 paper, 2019). "Additionally, new potentially pathogenic variants were discovered for two disorders, including IGF2/INS-IGF2 in mitochondrial disease and FBN3 in Klippel–Trenaunay–Weber syndrome." (PMID 31852928, 2019).
neurodevelopmental disorder (1 paper, 2022). A behavioral and cognitive disorder with onset during the developmental period that involves impaired or aberrant development of intellectual, motor, or social functions. "The FBN3 expression pattern in the developing and adult central nervous system could explain the neurodevelopmental disorder shown by the current and previous cases, a clinical feature that is vice versa absent in the other fibrillin-related diseases." (PMID 35910214, 2022).
skeletal dysplasia (1 paper, 2024). Any Mendelian diseases that affects growth and development of the skeleton. "Mutations in FBN3 have been associated with skeletal dysplasias and connective tissue abnormalities, which aligns with the skeletal and renal manifestations observed in this patient." (PMID 38919843, 2024).
FBN3 also shares sentences with these, for which no sentence is quoted: asthma (1 paper); atherosclerosis (1); autoimmune disease (1); cancer (1); Cognitive impairment (1); developmental delay (1); Hypertension (1); hypothyroidism (1); insulin-resistant diabetes mellitus (1); lymphoma (1); metabolic syndrome (1); psoriatic arthritis (1); Strabismus (1); systemic lupus erythematosus (1).